TRIM25 (tripartite motif containing 25)
Description:
Functions as a ubiquitin E3 ligase and as an ISG15 E3 ligase. Involved in innate immune defense against viruses by mediating ubiquitination of RIGI and IFIH1. Mediates 'Lys-63'-linked polyubiquitination of the RIGI N-terminal CARD-like region and may play a role in signal transduction that leads to the production of interferons in response to viral infection. Mediates 'Lys-63'-linked polyubiquitination of IFIH1. Promotes ISGylation of 14-3-3 sigma (SFN), an adapter protein implicated in the regulation of a large spectrum signaling pathway. Mediates estrogen action in various target organs. Mediates the ubiquitination and subsequent proteasomal degradation of ZFHX3. Plays a role in promoting the restart of stalled replication forks via interaction with the KHDC3L-OOEP scaffold and subsequent ubiquitination of BLM, resulting in the recruitment and retainment of BLM at DNA replication forks (By similarity). Plays an essential role in the antiviral activity of ZAP/ZC3HAV1; an antiviral protein which inhibits the replication of certain viruses. Mechanistically, mediates 'Lys-63'-linked polyubiquitination of ZAP/ZC3HAV1 that is required for its optimal binding to target mRNA. Also mediates the ubiquitination of various substrates implicated in stress granule formation, nonsense-mediated mRNA decay, nucleoside synthesis and mRNA translation and stability. Participates in autophagy suppression by ubiquitinating and degrading p62/SQSTM1.
Synonyms: EFP; RNF147; ZNF147; Z147
Tractability: PROTAC: UniProt records ubiquitination sites on it; ubiquitination databases record sites on it; its protein half-life has been measured.
Target class: Enzyme; Transferase
Gene: Protein-coding gene on chromosome 17 (56,836,387 to 56,914,080, reverse strand). Ensembl gene ENSG00000121060.
Subcellular location: Cytoplasm; Cytoplasm, Stress granule; Nucleus
Subcellular location (Human Protein Atlas): Cytosol; Nucleoplasm; Nuclear bodies
Pathways (Reactome):
Immune System: DDX58/IFIH1-mediated induction of interferon-alpha/beta; ISG15 antiviral mechanism; Interferon gamma signaling; Modulation of host responses by IFN-stimulated genes; NF-kB activation through FADD/RIP-1 pathway mediated by caspase-8 and -10; Negative regulators of DDX58/IFIH1 signaling; PKR-mediated signaling; TRAF3-dependent IRF activation pathway; TRAF6 mediated IRF7 activation; TRAF6 mediated NF-kB activation
Disease: Dengue virus activates/modulates innate and adaptive immune responses; Evasion by RSV of host interferon responses; RSV-host interactions; SARS-CoV-1 activates/modulates innate immune responses; SARS-CoV-2 activates/modulates innate and adaptive immune responses
DNA Repair: Termination of translesion DNA synthesis
Metabolism of proteins: Ovarian tumor domain proteases
Gene Ontology:
Molecular function: cadherin binding; protein binding; RIG-I binding; RNA binding; transcription coactivator activity; ubiquitin protein ligase activity; ubiquitin-protein transferase activity
Biological process: antiviral innate immune response; cytoplasmic pattern recognition receptor signaling pathway; ERAD pathway; negative regulation of autophagy; positive regulation of canonical NF-kappaB signal transduction; protein K48-linked ubiquitination; protein monoubiquitination; response to estrogen; response to oxidative stress; RIG-I signaling pathway; ubiquitin-dependent protein catabolic process; innate immune response; regulation of protein localization; defense response to virus; host-mediated suppression of symbiont invasion; positive regulation of DNA-templated transcription; protein ubiquitination; response to vitamin D; suppression of viral release by host
Cellular component: cytoplasm; cytoplasmic stress granule; cytosol; nucleoplasm; nucleus
Genetic constraint (gnomAD): Loss-of-function variants: 45 observed, 62.63 expected, observed/expected ratio (o/e) 0.72, 90% interval 0.56 to 0.92. The upper end of that interval is the gene's LOEUF score, 0.92, which puts it in group 3 of 6, group 1 being the genes least tolerant of losing a copy. Missense variants: 711 observed, 796.65 expected, observed/expected ratio (o/e) 0.89, 90% interval 0.84 to 0.95. Synonymous variants: 317 observed, 329.86 expected, observed/expected ratio (o/e) 0.96, 90% interval 0.88 to 1.05.
Homologues: Orthologues: chimpanzee TRIM25 (99% identical), pig TRIM25 (78% identical), dog TRIM25 (77% identical), mouse Trim25 (74% identical), rat Trim25 (73% identical), guinea pig TRIM25 (70% identical), macaque TRIM25 (66% identical), tropical clawed frog trim25 (41% identical). Paralogues in human: MID1 (21% identical), MID2 (20% identical), TRIM39 (19% identical), TRIM47 (19% identical), TRIM60 (18% identical), TRIM41 (18% identical), TRIM7 (18% identical), TRIM27 (17% identical), TRIM68 (17% identical), TRIM58 (17% identical), TRIM11 (17% identical), TRIM4 (17% identical), and 68 more.
Diseases named in the same sentence as TRIM25 in open-access papers:
TRIM25 is named in the same sentence as 91 diseases in open-access papers, as found by Europe PMC text mining. Sharing a sentence is not in itself a finding about the gene and the disease. The quoted sentences say what the papers report.
viral infection (84 papers, 2008 to 2026). "During viral infection, TRIM25 can mediate K63-linked TRAF2 ubiquitination, which activates TNFα-induced NF-kB signaling." (PMID 40431746, 2025). "During viral infection, TRIM25 mediates lysine 63- linked ubiquitination of the N-terminal 2CARDs of the viral RNA sensor retinoic acid-inducible gene I (RIG-I) to facilitate IFN-I production and antiviral immunity." (PMID 38589930, 2024). "In response to viral infection, TRIM25 has previously been reported to mediate the K48-linked ubiquitination of MAVS causing its proteasomal degradation to negatively regulate IFN-β production, and the K63-linked ubiquitination of the RIG-I receptor." (PMID 34445801, 2021). "The importance of TRIM25 in RIG-I signaling was illustrated by reduced IFN production in TRIM25−/− mouse embryonic fibroblasts and a corresponding susceptibility to viral infection." (PMID 33968942, 2021). "The association between lncRNA and TRIM25 occurs even in resting cells and promotes TRIM25-mediated K63-linked polyubiquitination of RIG-I during viral infection." (PMID 32670286, 2020). "We found that BPLF1 causes the sequestration of TRIM25 into aggregates that are distinct from the stress granules induced by viral infections and co-localize with the autophagy receptor p62/SQSTM1." (PMID 31710640, 2019). "Evidence also suggests that TRIM25 produces unanchored K63-linked polyubiquitin chains in response to viral infection and delivered them to RIG-I." (PMID 29354136, 2017). "Functionally, the TRIM25 gene encodes TRIM25, an inducible E3 ubiquitin ligase, which is predominantly located in the cytosol and can be redistributed into the organelles within a cell following viral infection." (PMID 40431746, 2025). "We then examined proteins that display a preference for association with TRIM25-R54P under mock and viral infection conditions, and found that several of these are necessary for TRIM25 antiviral activity, identifying them as potential TRIM25 substrates mediating viral inhibition." (PMID 36067236, 2022). "Conversely, the antiviral functions of TRIM25 are inhibited by viral proteins and RNAs through their interactions, as well as by the viral infection-mediated upregulation of certain miRNAs." (PMID 40431746, 2025). "This multifaceted domain structure allows TRIM25 to engage in diverse biological activities, making it a pivotal component in the cellular response to viral infection." (PMID 40431746, 2025). "Both rely on the expression of interferon-stimulated genes (ISGs) and the ubiquitination pathway mediated by TRIM25 to mount antiviral immune responses, effectively defending against viral infections." (PMID 40170840, 2025). "A study has reported that upregulated TRIM25 expression can limit SARS-CoV-2 replication, suggesting that upregulated TRIM25 expression is a viral-infection-induced compensative antiviral response." (PMID 40431746, 2025). "Alternatively, is it possible that hsRNAs contribute to viral infection by antagonizing intrinsic antiviral defense mechanisms, similar to how sfRNA generated by dengue virus interacts with the ubiquitin ligase TRIM25 to block interferon production ?" (PMID 40431677, 2025). "Together, these results suggest that viral infection promotes TRIM25 co-condensation with G3BP1, which in turn inhibits viral infection." (PMID 38750080, 2024). "In uninfected cells, endogenous SH3KBP1 interacted with TRIM25, and this interaction was significantly enhanced after viral infection." (PMID 39466846, 2024). "The results showed that with the progression of viral infection, TRIM25 protein expression decreased gradually." (PMID 39480084, 2024). "The formation of TRIM25 multimers acts a pivotal role in RIG-I 2CARDs ubiquitination—a crucial modification necessary for the optimal IFN production in response to viral infection." (PMID 38589930, 2024).
viral infection (continued). "Taken together, the present findings showed that the PRRSV replication restriction factor TRIM25 inhibited the degradation of ubiquitinated protein aggregates during viral infection by suppressing p62-mediated autophagy." (PMID 39480084, 2024). "TRIM25 binding sites in cellular RNAs substantially differ in infected and mock cells, with only ~22% of overlapping targets, supporting that TRIM25 RNA-binding activity is regulated by virus infection." (PMID 39353916, 2024). "For example, Trim25, belongs to the C-IV family, induces the Lys 63-linked ubiquitination of RIG-I to regulate innate immunity to viral infection." (PMID 39349450, 2024). "During the early stages of viral infection, SH3KBP1 recruited TRIM25 and enhanced the K63-linked polyubiquitination of RIG-I, thereby enhancing the expression IFN-β and ISGs." (PMID 39466846, 2024). "TRIM16 and TRIM25 are E3 ubiquitin ligases that play key roles in the host’s immune response to viral infections." (PMID 39211041, 2024). "The expression of TRIM25 and its subsequently mediated ubiquitination are regulated by several mechanisms in virus infection." (PMID 37628607, 2023). "RIG-I is a viral RNA sensor and plays a crucial role in inducing IFN-mediated, host protective innate immunity against viral infection, and TRIM25 was also found to be essential during this process." (PMID 37391858, 2023). "Ubiquitin-specific protease 15 is recruited to TRIM25 in sendai virus infection, and then deubiquitylates TRIM25 to regulate RIG-I-mediated type-I IFN response." (PMID 37628607, 2023). "Further studies need to be performed to determine their synergistic effects on viral infection and functional consequences of their ubiquitination by TRIM25." (PMID 36067236, 2022). "Compared with the cellular infection experiment, the protein expression of G3BP2 and TRIM25 increased gradually in the early stage of virus infection." (PMID 36560452, 2022). "While TRIM25 has been shown to complex with ZAP in the context of several different viral infections, its ligase activity has only been tied to its participation in blocking translation of incoming RNA genomes of alphavirus (family Togaviridae)." (PMID 36067236, 2022). "Viral infection can lead to oxidative stress and degradation of viral proteins via proteasomes, and the TRIM25 ubiquitylation pathway." (PMID 35859153, 2022). "While BRMS1L has been described as a metastatic suppressor gene, TRIM25 has been involved in numerous cellular processes including regulation of innate immune response against viral infection." (PMID 34899750, 2021). "While only TRIM25 participated in the defense response of the host against viral infection according to Go functional analysis results." (PMID 34516573, 2021). "TRIM25 is an important protein that is involved in innate immune defense especially after viral infection." (PMID 33947096, 2021). "The results showed that RTN3 interacted with TRIM25 under basal conditions and was slightly strengthened upon viral infection." (PMID 34313226, 2021). "We identified EP300, MOV10, RELA, and TRIM25 as top candidates, and more than 60 additional proteins involved in the epigenetic response during viral infection that has therapeutic potential." (PMID 34031419, 2021). "At the early stage of viral infection, lncRNA z3h7a in the cytoplasm binds to tripartite motif-containing protein 25 (TRIM25) and activates RIG-I." (PMID 35062254, 2021). "Lnc-lsm3b also reduces IFN-I production to maintain immune homeostasis, and its overexpression in L929 cells interferes with TRIM25-mediated K63 junction ubiquitination of RIG-I during viral infection." (PMID 35062254, 2021). "For example, the endogenous protein cyclophilin A, which normally competes with TRIM25 for MAVS binding, is upregulated by viral infection, thereby effectively inhibiting TRIM25-mediated MAVS ubiquitination and degradation." (PMID 32536927, 2020).
viral infection (continued). "TRIM25 overexpression reverses the defective innate response mediated by Dot1L inhibition elicited upon virus infection or by overexpression of RIG-I signaling intermediates." (PMID 32188146, 2020). "Of the most recently identified ZAP-interacting partners, TRIM25 has been shown to be targeted to SG during virus infection." (PMID 31116799, 2019). "For example, lnczc3h7a can bind to tripartite motif protein 25 (TRIM25) for facilitating TRIM25-mediated K63-linked ubiquitination of RIG-I, thereby enhancing innate immune responses to viral infection." (PMID 31623059, 2019). "For example, TRIM25 mediated K63-ubiquitination of RIG-I is one of the first events following viral infection." (PMID 30157886, 2018). "USP15 binds to TRIM25 in viral infections, detaching the K48-linked ubiquitin chains assembled by LUBAC on TRIM25, thereby stabilizing the TRIM25 protein levels and promoting a sustained antiviral response." (PMID 29018447, 2017). "Studies in mouse embryonic fibroblasts deficient in TRIM25 demonstrated its importance in RIG-I activation and IFN-β production in response to viral infection." (PMID 29018447, 2017). "For example, TRIM25 and Riplet/RNF135/REUL induce K63-linked ubiquitination within the CARD domains of RIG-I following viral infection, a modification which is necessary for interaction with IPS-160–62." (PMID 29109527, 2017). "Strikingly, knockout of Trim25 had marginal effect on IFN production in MEFs in response to virus infection, while knockout of Riplet abolished IFN production completely." (PMID 28469175, 2017). "When a host cell detects a viral infection, TRIM25 induces unanchored K63 ubiquitination of RIG-I, thereby activating RIG-I antiviral defense responses." (PMID 26996158, 2016). "It has been shown that TRIM25 plays a critical role in inducing interferon production in response to viral infection via ubiquitylation of RIG-1." (PMID 24810856, 2014). "We next determined the ubiquitination of endogenous RIG-I in WT and TRIM25 −/− MEFs upon PR8 virus infection." (PMID 23209422, 2012). "In our study, we also found that TRIM25 is upregulated upon viral infection." (PMID 40857262, 2025). "Furthermore, TRIM25 can bind viral RNAs to regulate the defense against viral infection in innate immunity." (PMID 40431746, 2025). "Previous studies have indicated that multiple virus infection affect the expression of TRIM25." (PMID 38589930, 2024). "The first, TRIM25, is an E3 ubiquitin ligase enzyme that regulates the K63-linked ubiquitination of RIG-I, which is essential for RIG-I downstream signaling and the innate immune response to viral infections." (PMID 38627659, 2024). "Compared with the control group, TRIM25 expression was upregulated in all tested tissues after viral infection: the heart, liver, spleen, kidney, thymus, and bursa of Fabricius exhibited ~7.7, 2.6, 5.9, 3.9, 1.5, and 1.5-fold increases after DHAV-1 infection at 24 hpi, respectively." (PMID 37391858, 2023). "TRIM25 is widely involved in the host’s resistance to viral infection." (PMID 37628607, 2023). "These include DOCK2, which is known to activate RAC1/RAC2 genes required for implantation, and TRIM25, a gene involved in innate immune response against viral infection, mediating estrogen action and whose downregulation during embryogenesis in medaka has been shown to result in apoptosis." (PMID 37789509, 2023). "TRIM25 regulates innate immune response through several mechanisms in viral infection." (PMID 37628607, 2023). "We identified NME1 and PABPC4 as TRIM25-R54P-specific interactors during viral infection." (PMID 36067236, 2022). "RIG-I and TRIM25 are important initiators of the early immune response to viral infection." (PMID 34835165, 2021). "However, virus infection can promote the interaction of lnczc3h7a and TRIM25, thus augmenting RIG-I mediated antiviral immune response." (PMID 34804040, 2021).